GJB5 (gap junction protein beta 5)
Description:
One gap junction consists of a cluster of closely packed pairs of transmembrane channels, the connexons, through which materials of low MW diffuse from one cell to a neighboring cell.
Synonyms: Cx31.1
Tractability: Antibody: UniProt places it where antibodies can reach, with medium confidence; UniProt predicts a signal peptide or a membrane-spanning region; its Gene Ontology location is reachable by antibodies, with medium confidence.
Gene: Protein-coding gene on chromosome 1 (34,755,034 to 34,758,512, forward strand). Ensembl gene ENSG00000189280.
Subcellular location: Cell membrane; Cell junction, gap junction
Pathways (Reactome):
Vesicle-mediated transport: Gap junction assembly
Gene Ontology:
Molecular function: protein binding; gap junction channel activity
Biological process: cell-cell signaling; epidermis development; cell communication; transmembrane transport
Cellular component: connexin complex; gap junction; plasma membrane
Genetic constraint (gnomAD): Loss-of-function variants: 3 observed, 3.42 expected, observed/expected ratio (o/e) 0.88, 90% interval 0.39 to 1.81. That is too few expected variants to judge how well the gene tolerates losing a copy. Missense variants: 333 observed, 376.73 expected, observed/expected ratio (o/e) 0.88, 90% interval 0.81 to 0.97. Synonymous variants: 146 observed, 153.05 expected, observed/expected ratio (o/e) 0.95, 90% interval 0.83 to 1.09.
Homologues: Orthologues: chimpanzee GJB5 (99% identical), macaque GJB5 (99% identical), guinea pig GJB5 (84% identical), pig GJB5 (84% identical), dog GJB5 (81% identical), mouse Gjb5 (77% identical), rat Gjb5 (75% identical), zebrafish gjb10 (53% identical). Paralogues in human: GJB4 (57% identical), GJB3 (51% identical), GJB7 (45% identical), GJB1 (42% identical), GJB6 (41% identical), GJB2 (40% identical), GJA1 (36% identical), GJA8 (36% identical), GJA3 (35% identical), GJA10 (34% identical), GJA9 (34% identical), GJA4 (34% identical), and 8 more.
Diseases named in the same sentence as GJB5 in open-access papers:
GJB5 is named in the same sentence as 24 diseases in open-access papers, as found by Europe PMC text mining. Sharing a sentence is not in itself a finding about the gene and the disease. The quoted sentences say what the papers report.
non-small cell lung carcinoma (5 papers, 2015 to 2024). A group of at least three distinct histological types of lung cancer, including non-small cell squamous cell carcinoma, adenocarcinoma, and large cell carcinoma. "Importantly, loss of the connexion protein Cx31.1, also known as the gap junction beta 5 (GJB5), promotes non-small cell lung cancer, indicating that GJB5 may act as a tumor suppressor protein." (PMID 38956497, 2024).
melanoma (2 papers, 2019 to 2025). A malignant, usually aggressive tumor composed of atypical, neoplastic melanocytes. "In GSE8401 arrays, metastatic melanomas from xenograft models showed downregulated GJA1 (Cx43; LogFC = −2.8; p < 0.001), GJB3 (Cx31; LogFC = −1.8; p < 0.001) and GJB5 (Cx31.1; LogFC = −1.1; p < 0.001) gene expression compared to primary melanomas." (PMID 30717194, 2019). "Additionally, GJB5 expression was lower in metastatic melanoma lesions compared to primary lesions, suggesting a potential mechanism contributing to melanoma aggressiveness." (PMID 40141179, 2025). "In melanoma cell lines, miR-335-5p was shown to reduce the expression of GJB5." (PMID 40141179, 2025). "In datasets using GSE3189 arrays, melanomas showed downregulated GJA1 (Cx43; LogFC = −4.1; p < 0.001), GJB3 (Cx31; LogFC = −3.4; p < 0.001), GJB5 (Cx31.1; LogFC = −3.3; p < 0.001) and upregulated GJB1 (Cx32; LogFC = +1.5; p < 0.001) gene expression compared to nevi." (PMID 30717194, 2019).
pancreatic cancer (2 papers, 2020 to 2025). "The higher expression of GJB5 (Gap Junction β5, a member of the β-type connexin family) is considered a predictor of poor clinical outcomes in pancreatic cancer patients; however, the information about its contribution in pancreatic cancer pathogenesis is scarce." (PMID 40680814, 2025). "Furthermore, five genes (KRT19, ALDOA, CLDN4, RAB27B, and GJB5) among the top 10 % coregulated genes were identified to have significantly elevated expression in pancreatic cancer compared to the normal pancreas." (PMID 40680814, 2025). "A total of 26 genes were found to be significantly associated with poor prognosis, while five of them, including SYT12, GJB5, RHOJ, GJB3 and IFI27, were of particular interest as they have not been previously associated with poor outcomes in pancreatic cancer cases." (PMID 32724299, 2020).
adenoma (1 paper, 2014). A neoplasm arising from the epithelium. "Marked increased expression of MUC17, the cell junction protein genes VSIG1 and GJB5, and the antiapoptotic gene REG4 were found in SSA/Ps, relative to controls and adenomas, were verified by qPCR analysis of additional SSA/Ps (n = 21) and adenomas (n = 10)." (PMID 24533081, 2014).
adenosquamous carcinoma (1 paper, 2025). A carcinoma composed of malignant glandular cells and malignant squamous cells. "Compared to normal cervical tissue (“Normal”), GJB5 expression was markedly elevated in adenocarcinoma, squamous cell carcinoma (SCC), and adenosquamous carcinoma." (PMID 40537499, 2025).
breast tumors (1 paper, 2014).
cervical cancer (1 paper, 2025). A primary or metastatic malignant neoplasm involving the cervix. "Results demonstrated a significant association between high GJB5 overexpression and reduced overall survival in cervical cancer patients." (PMID 40537499, 2025). "Conversely, GJB5 overexpression was associated with enhanced Akt-mTOR signaling in primary human cervical cancer cells." (PMID 40537499, 2025). "In our investigations into the underlying mechanisms of cervical cancer progression, we showed that GJB5 is integral to the activation of the Akt-mTOR signaling pathway." (PMID 40537499, 2025). "This study aims to investigate the expression, functional role, and potential underlying mechanisms of GJB5 in cervical cancer, as these aspects remain largely unexplored." (PMID 40537499, 2025). "Examination of TCGA data revealed a significant increase in GJB5 mRNA expression in cervical cancer tissues compared to normal cervical epithelium, with high levels of GJB5 correlating with poorer clinical outcomes, including reduced overall survival." (PMID 40537499, 2025). "Analysis of The Cancer Genome Atlas (TCGA) data demonstrated significantly increased GJB5 mRNA expression in cervical cancer tissues compared to normal cervical epithelium." (PMID 40537499, 2025). "To confirm the specificity of the observed effects of GJB5 silencing, we employed CRISPR/Cas9-mediated gene editing to generate GJB5 knockout (koGJB5) in priCC-1 cervical cancer cells." (PMID 40537499, 2025). "GJB5’s link to epidermal differentiation is particularly relevant as cervical cancer frequently originates in the squamous epithelium, which shares characteristics with epidermal tissue." (PMID 40537499, 2025). "Conversely, Gαi3 overexpression enhanced Akt phosphorylation in primary cervical cancer cells, and this effect was partially inhibited by GJB5 silencing." (PMID 40537499, 2025). "Our results strongly support GJB5 as a novel therapeutic target for cervical cancer based on compelling evidence from multiple analyses." (PMID 40537499, 2025). "To validate the role of GJB5 in multiple cervical cancer contexts, we expanded our investigation to additional cells, including the primary priCC-2 cervical cancer cells and the immortalized Caski and HeLa229 cell lines." (PMID 40537499, 2025). "Comprehensive analysis of all 20 patient samples reinforced the significant upregulation of GJB5 protein in cervical cancer tissues." (PMID 40537499, 2025). "This suggests a novel mechanism by which GJB5 contributes to Akt activation and cervical cancer progression." (PMID 40537499, 2025). "GJB5 knockdown or knockout led to diminished phosphorylation of Akt and S6 kinase, whereas GJB5 overexpression correlated with increased Akt-mTOR signaling in primary human cervical cancer cells." (PMID 40537499, 2025). "GJB5 expression is also elevated in cervical cancer tissues from locally treated patients and in a panel of primary and established cervical cancer cells." (PMID 40537499, 2025). "To further investigate GJB5 expression in cervical cancer cells, we examined both primary and immortalized cells." (PMID 40537499, 2025). "To investigate the possible functional role of GJB5 in cervical cancer malignant behaviors, we utilized lentiviral shRNA to knockdown (kd) GJB5 expression in priCC-1 primary human cervical cancer cells." (PMID 40537499, 2025). "Western blotting analysis conducted on four representative patients (Patient-1# to Patient-4#) demonstrated markedly heightened GJB5 protein expression in cervical cancer tissues relative to their paracancerous normal counterparts." (PMID 40537499, 2025). "Collectively, these findings underscore a consistent and significant overexpression of GJB5 in cervical cancer tissues and cells, suggesting its potential role in the pathogenesis of this disease." (PMID 40537499, 2025).
cervical cancer (continued). "To investigate the potential role of GJB5 on apoptosis, we again employed lentiviral shRNA to knockdown GJB5 expression in priCC-1 primary cervical cancer cells." (PMID 40537499, 2025). "Next, our study revealed a significant upregulation of GJB5 in cervical cancer tissues of locally-treated patients." (PMID 40537499, 2025). "Co-IP assays in priCC-1 and priCC-2 primary cervical cancer cells revealed a physical interaction between GJB5 and Gαi3." (PMID 40537499, 2025). "We demonstrated a physical interaction between GJB5 and Gαi3 through co-IP assays in both cervical cancer cells and fresh tumor tissues." (PMID 40537499, 2025). "Given the potential involvement of the Akt-mTOR pathway in GJB5-mediated cervical cancer cell progression in vitro, we examined the activation status of this pathway." (PMID 40537499, 2025). "To investigate the functional role of GJB5 in the in vivo growth of cervical cancer cells, we established subcutaneous xenograft models in nude mice using priCC-1 cells expressing either kdGJB5-sh2 or control (kdC) shRNA." (PMID 40537499, 2025). "Functional assays demonstrated a pronounced inhibitory effect of GJB5 silencing on key aspects of cervical cancer cell behaviors." (PMID 40537499, 2025). "Using the same kdGJB5-sh2 lentiviral construct, we observed consistent and robust downregulation of GJB5 mRNA expression across all three cervical cancer cell types, while GJB4 mRNA levels remained unaffected." (PMID 40537499, 2025). "To further investigate the role of GJB5 in apoptosis, we extended our studies to additional cervical cancer cells, including primary priCC-2 cells and the immortalized Caski and HeLa229 lines." (PMID 40537499, 2025). "Gene expression analysis of cervical cancer specimens from The Cancer Genome Atlas (TCGA) revealed significant dysregulation of GJB5 expression." (PMID 40537499, 2025). "Thus, GJB5 overexpression promotes several key malignant behaviors in cervical cancer cells, including increased proliferation, migration, and invasion." (PMID 40537499, 2025). "Our results indicated that both GJB5 mRNA and protein levels were significantly elevated in primary human cervical cancer cells (priCC-1 and priCC-2) and immortalized cervical cancer cell lines (Caski and HeLa229) compared to primary cervical epithelial cells (priCEpi-1 and priCEpi-2)." (PMID 40537499, 2025). "This study investigated GJB5’s expression and functional significance in cervical cancer." (PMID 40537499, 2025). "This study identified a novel mechanism by which GJB5 promotes Akt signaling in cervical cancer." (PMID 40537499, 2025). "Next, we propose that ectopic GJB5 overexpression might promote malignant behaviors of cervical cancer cells." (PMID 40537499, 2025). "Collectively, these findings underscore GJB5 as a key oncogenic driver in cervical cancer and indicate that targeting GJB5 could be a promising therapeutic approach for this disease." (PMID 40537499, 2025). "The knockdown of GJB5 resulted in a marked reduction in the growth of cervical cancer xenografts." (PMID 40537499, 2025). "In priCC-1 primary human cervical cancer cells, GJB5 silencing via shRNA (kdGJB5-sh1, kdGJB5-sh2) or CRISPR/Cas9-mediated knockout (koGJB5-sg1, koGJB5-sg2) significantly reduced phosphorylation of Akt (Ser-473) and its downstream target, S6K1, as determined by western blotting analysis." (PMID 40537499, 2025). "Additionally, the knockdown of GJB5 resulted in a significant reduction in the growth of cervical cancer xenografts, reinforcing its potential as a promising target for therapeutic intervention in cervical cancer management." (PMID 40537499, 2025). "The observation that GJB5 silencing or depletion exerts pleiotropic effects on cervical cancer cell behaviors, including inhibition of viability, proliferation, and migration, and enhancement of apoptosis, suggests that GJB5 may regulate key oncogenic signaling cascades." (PMID 40537499, 2025).
cervical cancer (continued). "The downregulation of GJB5 through shRNA or CRISPR/Cas9 gene knockout techniques significantly impaired the viability, proliferation, and migratory capacity of cervical cancer cells, while concurrently inducing apoptotic processes." (PMID 40537499, 2025). "However, in contrast to the cervical cancer cells, GJB5 silencing in primary epithelial cells did not result in a significant inhibition of cell proliferation or a decrease in cell viability." (PMID 40537499, 2025). "To determine whether Akt inactivation mediates the anti-cervical cancer effects of GJB5 silencing, we introduced a constitutively-active Akt1 (caAkt1, S473D) mutant into GJB5-silenced priCC-1 cells, and it completely restored Akt-S6K1 phosphorylation without affecting GJB5 protein expression." (PMID 40537499, 2025).
cervical squamous cell carcinoma (1 paper, 2025). A squamous cell carcinoma arising from the cervical epithelium. "To explore the potential functional implications of GJB5 upregulation in cervical squamous cell carcinoma, we performed correlation analysis of GJB5 expression with all other genes within the epithelial cell cluster." (PMID 40537499, 2025). "Further analysis revealed a significant increase in GJB5 expression in epithelial cells from cervical squamous cell carcinoma samples compared to paracancer normal tissue." (PMID 40537499, 2025). "Furthermore, pan-cancer analyses indicate variable GJB5 expression across malignancies, with notable reports of elevated GJB5 mRNA expression in cervical squamous cell carcinoma." (PMID 40537499, 2025). "Thus, the scRNA-seq analysis demonstrates overexpression of GJB5 in the epithelial population of cervical squamous cell carcinoma, suggesting its potential involvement in tumor progression and highlighting its potential as a therapeutic target." (PMID 40537499, 2025). "The results revealed a distinct expression pattern of GJB5 in cervical squamous cell carcinoma." (PMID 40537499, 2025). "Furthermore, single-cell RNA sequencing confirmed GJB5 overexpression specifically within the malignant tumor cell population of cervical squamous cell carcinoma." (PMID 40537499, 2025).
colorectal cancer (1 paper, 2021). A primary or metastatic malignant neoplasm that affects the colon or rectum. "Among different members of the connexin family, GJB5 has not been described in association with colorectal cancer or RAS signaling, and the role of GJB5 in colorectal carcinogenesis remains largely unknown." (PMID 33982211, 2021).
gastric cancer (1 paper, 2025). A primary or metastatic malignant neoplasm involving the stomach. "Tumor cell regions were demarcated using gastric cancer-specific marker genes (KRT17/PRAME/GNGT1/GJB5/PI3)." (PMID 40452847, 2025).
squamous cell carcinoma (1 paper, 2025). A carcinoma arising from squamous epithelial cells. "This adverse prognostic impact of elevated GJB5 expression was particularly evident in patients with squamous cell carcinoma." (PMID 40537499, 2025). "This upregulation was further corroborated by paired sample analysis, which demonstrated a significant increase in GJB5 expression in squamous cell carcinoma compared to normal tissues from the same patients." (PMID 40537499, 2025).
tumor (10 papers, 2014 to 2025). "GJB5, a gap junction protein, is traditionally viewed as a tumor suppressor, and its loss of connexin-mediated communication is linked to cancer progression." (PMID 41394854, 2025). "Single-cell RNA sequencing corroborated GJB5 overexpression within the malignant tumor cell population." (PMID 40537499, 2025). "Notably, demethylation of GJB5 (particularly in LUSC) correlated with the observation that the mRNA expression of this gene was significantly upregulated in tumours." (PMID 30845770, 2019). "Gap junction proteins promote stromal-epithelial interactions in tumors, have a role in tumor progression and GJB3 and GJB5 regulate survival of some stem cells." (PMID 24533081, 2014).
cancer (6 papers, 2015 to 2025). A tumor composed of atypical neoplastic, often pleomorphic cells that invade other tissues. "Similar to the cancer cells, GJB5 mRNA expression was significantly downregulated in these cells following transfection with the kdGJB5-sh2 construct." (PMID 40537499, 2025).
GJB5 also shares sentences with these, for which no sentence is quoted: adenocarcinoma (1 paper); breast carcinoma (1); Hepatic steatosis (1); hyperplastic (1); infection (1); lung adenocarcinoma (1); lung carcinoma (1); metastatic melanoma (1); papilloma (1); skin cancer (1); velocardiofacial syndrome (1).